OPCML (opioid binding protein/cell adhesion molecule like)
Diseases named in the same sentence as OPCML in open-access papers (continued):
Sharing a sentence is not in itself a finding about the gene and the disease.
tumor (48 papers, 2004 to 2025). "This work demonstrated that the reported clinical mutations at these sites in different tumors inactivated OPCML’s tumor suppressor activity." (PMID 40699804, 2025). "The results presented above demonstrate the strong impact that single point mutations have in inactivating OPCML’s tumor suppressor function(s) in vitro." (PMID 31316070, 2019). "Exonic deletions were detected in the PPP2R5A, FHIT, LRP1B, and OPCML tumor suppressor genes, as well as in genes implicated in cellular proliferation (CCNB1, ANAPC5, PIK3C2A) and DNA repair (SMARCA5)." (PMID 30836646, 2019). "Decreased OPCML expression had a significant association with unfavorable tumor stage (p = 0.007) and grading (p < 0.001)." (PMID 28407749, 2017). "Beyond OPCML’s chaperoning effects on RTKs into cell-membrane lipid rafts, the analyses reported here regarding functional pathway enrichment emphasize deeper secondary association impacts of OPCML with other cellular processes that also impact tumor growth." (PMID 40699804, 2025). "Besides NF2, the same study found that several other tumor suppressors, including OPCML, Cav-1, and UGT2B17, showed a loss of tumor suppressive effects." (PMID 39796693, 2024). "OPCML exerts its tumor suppressor effect by inhibiting several cancer hallmark phenotypes in vitro, and abrogating tumorigenesis in vivo, by downregulating/inactivating a specific spectrum of Receptor Tyrosine Kinases (RTKs), including EphA2, FGFR1, FGFR3, HER2, HER4, and AXL." (PMID 36835855, 2023). "To test the role of OPCML dimerization in tumor suppression, we investigated the R65L mutation." (PMID 31316070, 2019). "However, association of methylated OPCML and DcR1 with patient clinicopathological data supports their role in tumour progression." (PMID 21448164, 2011). "RNA sequencing results revealed significant differences in gene expression, with key genes (upregulated CXCR4, OPCML, and S100A2, and downregulated ATP1A3, CHL1, HLA-DRA, and IL-1β) associated with tumor invasiveness." (PMID 41374320, 2025). "In this work, we demonstrate that in addition to this primary effect on RTKs, OPCML can influence a broader range of cellular activities that reinforce the potency of its tumor suppression effects." (PMID 40699804, 2025). "Mechanistic work in epithelial cancers has shown that OPCML can act as a cell surface “repressor–adaptor”: by engaging and modulating RTKs, it blunts the downstream signaling and tumor motility." (PMID 41561740, 2025). "Therapeutics: There have been a range of studies looking at OPCML restoration as a therapeutic agent to restore its natural tumor suppressor functions when those activities are lost due to OPCML gene silencing." (PMID 40699804, 2025). "OPCML is a multi-functional, pleiotropic, tumor suppressor protein that can inhibit tumor formation via multiple, distinct primary and secondary pathways that significantly impact patient survival outcomes, consistent with its known functional biology." (PMID 40699804, 2025). "OPCML is unique in exerting its tumor suppressive function on the external side of the cell membrane through RTK modulation in lipid raft microdomains." (PMID 40699804, 2025). "OPCML is a member of this family and its inactivation is an important control point in oncogenesis and tumor growth." (PMID 40699804, 2025). "The tumor suppressor activity of OPCML, particularly within the tumor micro-environment, is clearly antagonistic to the action of CLRs in tumor formation." (PMID 40699804, 2025). "One strategy involves using recombinant OPCML protein therapeutically to reintroduce its tumor-suppressive effects through binding the ECD of RTKs at the external leaflet of the cell membrane within the lipid raft." (PMID 40699804, 2025). "OPCML is a potent tumor suppressor exposed on the cell surface, to which it is anchored by a glycosylphosphatidylinositol (GPI) group." (PMID 36835855, 2023).
tumor (continued). "The most investigated gene-specific methylation biomarkers were RASSF1A, BRCA1, and OPCML, all being tumor-suppressor genes previously reported to be involved in tumorigenesis and methylated in multiple solid cancers." (PMID 36788585, 2023). "Genes such as OPCML have been found to be silenced in tumors, and when reactivated, they lead to cancer tumor inhibition." (PMID 36672162, 2023). "It is established that the IgLON family member OPCML acts as a tumor suppressor by eliciting the downregulation or the inhibition of RTKs, such as EphA2, FGFR1, FGFR3, HER2, HER4, and AXL." (PMID 37765276, 2023). "As strong tumor suppressors and brain-specific secretory proteins, both OPCML and LGI1 are worth further investigation in GBM, and the strong binding affinity with TMZ observed in the present work indicates their potential as novel targets for TMZ." (PMID 36364024, 2022). "Another tumor suppressor gene found hyper-methylated in our study was OPCML (Opioid Binding Protein/Cell Adhesion Molecule Like)." (PMID 34277443, 2021). "Opioid-binding protein/cell adhesion molecule-like (OPCML) is a GPI-anchored protein functioning as a tumour-suppressor gene that attenuates multiple receptor tyrosine kinases." (PMID 35004315, 2021). "The human ortholog of DIP-ε is OPCML, an immunoglobulin protein best characterized as a tumor suppressor, and there is currently no reported role for either gene during bacterial infections." (PMID 33789347, 2021). "OPCML is a frequently inactivated tumor suppressor in multiple types of human cancer, predominantly through somatic methylation of the promoter region." (PMID 31316070, 2019). "We analyzed tumor DNA sequence data from the TCGA and COSMIC databases in order to identify possible clinical OPCML mutations." (PMID 31316070, 2019). "These included genes with homologs involved in tumor suppression (OPCML), cell growth regulation (CDKL3), DNA repair (FANCL), and innate immunity (TMED7-TICAM2)." (PMID 30845962, 2019). "Additional studies assessing larger cohorts are required to confirm the importance of OPCML methylation prior to tumor development." (PMID 30555700, 2018). "OPCML-pcDNA 3.1 transfection led to the significant reduction of the tumor volume formed by SGC-7901 cells in nude mice (P < 0.01)." (PMID 28407749, 2017). "Of note, tumors with more advanced tumor stages T3 and T4 tended to exhibit higher rates of low expression of OPCML compared with tumor stages T1 and T2 (P = 0.007)." (PMID 28407749, 2017). "Because apoptosis was also frequently associated with cell growth inhibition by tumor suppressor, Annexin V-FITC/PI flow cytometric analysis was used to determine the effect of ectopic OPCML expression on apoptosis of SGC-7901 and BGC-823 cells." (PMID 28407749, 2017). "When the in vivo experiment was concluded till the 27th day, mice with OPCML transfectants had a 66.7% decrease in tumor weight as compared to the empty vector (P <0.001)." (PMID 28407749, 2017). "OPCML was shown to be a tumor suppressor and inactivated by DNA methylation in a variety of cancer types." (PMID 28396702, 2017). "OPCML probably functions as a tumor suppressor through interacting with other IgLONs to form heterodimeric complex involved in signal transduction." (PMID 18714356, 2008). "Among the IgLON family, OPCML was the first member reported to possess tumor suppressor functions in epithelial ovarian cancer, being frequently silenced genetically and epigenetically at the early step of ovarian carcinogenesis." (PMID 18714356, 2008). "Ectopic expression of OPCML in tumor cell lines with endogenous silencing led to strong inhibition of cell colony formation, demonstrating that OPCML acts as a broad tumor suppressor." (PMID 18714356, 2008).
tumor (continued). "One of the principal functions of OPCML as a tumor suppressor protein is to inactivate receptor tyrosine kinases (RTKs) by binding and chaperoning RTKs to the lipid raft followed by dephosphorylation of the activated RTK and subsequently driving endocytosis, leading to degradation of that RTK." (PMID 40699804, 2025). "Beyond physiology, OPCML shows tumor-suppressive activity in epithelial cancers." (PMID 41561740, 2025). "Thus, the cellular-level impacts of OPCML are far reaching through many mechanisms of tumor progression and disease severity." (PMID 40699804, 2025). "With a large proportion of mutations being present in dimerization domain D1, we hypothesized an important role for D1 in mediating OPCML’s tumor suppressor functions." (PMID 31316070, 2019). "Collectively, cfDNA methylation of OPCML may potentially be used for monitoring tumor recurrence and response to treatment in CCA." (PMID 30832707, 2019). "BRCA1 is methylated in up to 30% of these tumours and OPCML is methylated in over 80% of OT." (PMID 31450846, 2019). "OPCML expression was markedly reduced in tumor tissues and cancer cell lines." (PMID 28407749, 2017). "A number of publications emphasize the role of OPCML as tumor-suppressor in different tumor types." (PMID 28210208, 2017). "Likewise, OPCML, an opioid receptor and putative tumor suppressor thought to play a role in adhesion, appears to become DNA methylated late, showing hypermethylation mainly in adenocarcinoma." (PMID 21731750, 2011). "We further demonstrated that OPCML acts as a broad tumor suppressor for multiple tumor types." (PMID 18714356, 2008). "Thus, through functional epigenetics, we identified OPCML as a broad tumor suppressor, which is frequently inactivated by methylation in multiple malignancies." (PMID 18714356, 2008). "Thus, our results demonstrate that OPCML is a broad functional tumor suppressor that is epigenetically silenced in multiple tumors." (PMID 18714356, 2008). "Through these domains, OPCML may bind directly to growth promoting or inhibitory molecules and modulate their functions in tumor cells." (PMID 18714356, 2008). "The treatment resulted in the restoration of OPCML-v1 expression in all tumor cell lines." (PMID 18714356, 2008). "The downregulation of OPCML in multiple tumor cell lines might also result from genetic deletion, as it resides in the frequently deleted 11q25 locus." (PMID 18714356, 2008). "We thus sought to establish whether ectopic expression of OPCML-v1 could inhibit tumor cell clonogenicity." (PMID 18714356, 2008). "In addition, ectopic expression of OPCML in cancer cells significantly inhibited cell viability (p < 0.01) and colony formation (p < 0.001), arrest cell cycle in G0/G1 phase and induced apoptosis, and suppressed tumor formation in nude mice." (PMID 28407749, 2017). "Using primers specific to the common exons of OPCML transcripts, we found the expression of OPCML in several tumor cell lines (Hep3B, H292, SW480, L1236), where the OPCML-v1 and v2 were totally silenced, indicating transcription of OPCML from alternative unknown promoters." (PMID 18714356, 2008). "The most investigated genes were RASSF1A, BRCA1, OPCML, APC, HIC1, and HOXA9, all being tumor-suppressor genes." (PMID 36788585, 2023). "Of these, eight showed highly significant hypermethylation in tumor tissue (p < 0.0001): GDNF, MTHFR, OPCML, TNFRSF25, TCF21, PAX8, PTPRN2 and PITX2." (PMID 18616821, 2008). "Firstly, unlike intracellular tumor suppressors that are often difficult to replace pharmacologically, OPCML’s extracellular localization offers a more accessible therapeutic targeting approach for drug delivery." (PMID 40699804, 2025).
tumor (continued). "Lower expression of LSAMP and NTM, but not OPCML, were found in tumor parts compared with normal parts in six LUAD patients, and this was validated by public datasets, Oncomine® and TCGA." (PMID 34202934, 2021). "A number of tumor related genes map in 11q distal region: EST1, CHK1, BARX2, OPCML, FLI-1, their role in tumor development and progression in JS is still unknown." (PMID 19267933, 2009). "The frequent silencing of OPCML-v1 in multiple tumor cell lines and primary tumors but not normal epithelial tissues indicates that OPCML-v1 is likely a tumor suppressor." (PMID 18714356, 2008). "To further validate the gene expression of OPCML, LSAMP, and NTM, we retrieved data from Oncomine and TCGA cohorts with analysis showing higher expression of OPCML and lower expressions of LSAMP and NTM in tumor tissues compared with normal tissue with statistical significance in LUAD." (PMID 34202934, 2021). "Members of the IgLON family have been reported to homodimerize and/or heterodimerize for functionality, but it is not known whether OPCML dimerization is required for its tumor suppressor function." (PMID 31316070, 2019). "Moreover, exogenous expression of OPCML in carcinoma cells lacking its expression leads to dramatic growth inhibition suggesting OPCML as a tumour suppressor." (PMID 21448164, 2011). "Cells expressing WT OPCML did not form visible tumors nor ascites in any of the injected mice, while cells expressing the vector control and the three mutants were able to give rise to tumor dissemination and ascites, though to different extents depending on the mutation." (PMID 31316070, 2019). "Low-protein expression was found in 88% (59 out of 67) of OPCML-hypermethylated CCA, however, as the vast majority of tumours (89%) had no or very low OPCML expression, it was not feasible to statistically analyse the association between expression and methylation." (PMID 21448164, 2011). "Indeed, MTHFR, OPCML, TNFRSF25 and TCF21 show highly statistically significant differences (p < 1 × 10-6) between tumor and adjacent non-tumor tissues in our study." (PMID 18616821, 2008).
cancer (20 papers, 2007 to 2025). A tumor composed of atypical neoplastic, often pleomorphic cells that invade other tissues. "We found point mutations in the OPCML gene in 287 out of 28,132 patients and these were distributed across all cancer types." (PMID 31316070, 2019). "Our results suggest that clinically occurring somatic missense mutations in OPCML have the potential to contribute to tumorigenesis in a variety of cancers." (PMID 31316070, 2019). "In this study, we for the first time investigated the association between OPCML expression and clinicopathological features as well as prognosis of cancer patients." (PMID 28407749, 2017). "We examine expression across normal brain and cancers, evaluate survival associations, map the co-expression and interaction contexts, and ask whether loss of OPCML promotes aggressive phenotypes by releasing PI3K–AKT–mTOR signaling." (PMID 41561740, 2025). "Differential expression or DNA methylation of OPCML has been linked to several types of cancers." (PMID 37019990, 2023). "Epigenetic silencing of OPCML has been reported in a spectrum of human malignancies, including human UC, and loss of OPCML could spur cancer development by attenuating intercellular adhesion." (PMID 37958445, 2023). "The alterations of phosphorylation status of AKT and its substrate GSK3β, up-regulation of pro-apoptotic regulators including caspase-3, caspase-9 and PARP, and up-regulation of cell cycle regulator p27, were implicated in the biological activity of OPCML in cancer cells." (PMID 28407749, 2017). "OPCML–RTK interactions are documented in other cancers: mapping them in GBM would connect the surface biochemistry to the AKT/mTOR readouts observed here." (PMID 41561740, 2025). "Across the TCGA pan-cancer cohort, the expression of OPCML increased in tandem with the majority of the immune cell signatures, suggesting that tumors with higher transcript levels generally harbor denser immune infiltrates." (PMID 41561740, 2025). "EDA, SEMA3G, ENPP5, EMX2, and OPCML were favorable factors and had low expression levels in ccRCC tissues, whereas PCDHGC3 was a risk factor and highly expressed in cancer tissues." (PMID 36505496, 2022). "Based on GSE146552 and GSE155760, we validated that three CpG sites (cg16639665, cg23236270, cg15964611) in OPCML promoter region were significantly higher in cancer tissues compared to normal tissues." (PMID 33777925, 2021). "Here, we search for additional OPCML somatic mutations in the TCGA and COSMIC DNA sequencing databases from a panel of nearly 30,000 patients affected by different cancers." (PMID 31316070, 2019). "Whereas pre-treatment with WT OPCML protein completely blocked the serum-stimulated invasion of cancer cells into the matrix, the cells pre-treated with mutant protein were unable to impair invasion, corroborating our findings in transduced cells." (PMID 31316070, 2019). "OPCML promoter epigenetic silencing in the form of hypermethylation has been proposed as a potential biomarker of a range of cancers." (PMID 30555700, 2018). "The hypermethylation of OPCML and its consequential transcriptional silencing in a wide variety of cancers is indicative of its role as a tumor suppressor gene (TSG) as well as its role as a potential biomarker for cancer." (PMID 30555700, 2018). "A mammalian expression vector encoding full-length OPCML-v1 was transfected into colorectal (HCT116), esophageal (KYSE510) and prostate (PC3) carcinoma cell lines which had completely methylated and silenced endogeous OPCML-v1 promoter." (PMID 18714356, 2008). "Ecotopic expression of OPCML led to significant inhibition of both anchorage-dependent and -independent growth of carcinoma cells with endogenous silencing." (PMID 18714356, 2008). "We know that OPCML drives degradation of RTK signaling receptors in cancers." (PMID 40699804, 2025).